AR (androgen receptor)
Diseases named in the same sentence as AR in open-access papers (continued):
Sharing a sentence is not in itself a finding about the gene and the disease.
tumor (continued). "A number of studies from experimental models suggest a basal cell origin: thus, experiments of transformation with lentivirus containing ERG and androgen receptor genes of sorted luminal and basal cells provided evidence that only the latter ones displayed tumor formation." (PMID 31366128, 2019). "Additionally, we compared the correlation of M2 macrophage gene markers and AR, as well as tumor purity." (PMID 31355524, 2019). "Previous studies show that AKR1C3 has been upregulated in abiratarone resistant tumors, suggesting that, in the AR responsive phase, androgen biosynthesis is inhibited but that, in resistance phase, tumor cells acquire the capacity to overexpress AKR1C3 enzyme." (PMID 31638934, 2019). "AR-positive expression was defined as >1% of positively stained tumor cells." (PMID 31245286, 2019). "ARHGDIA and TAGLN2 have both previously been shown to repress AR transcriptional activity, and to have tumour-suppressive roles; their downregulation has clear implications for PC development, and further supports oncogenic activity of miR-346, 361-3p and -197." (PMID 31043708, 2019). "Importantly, treatment of tumor cells with a NOTCH γ-secretase inhibitor conferred an increased sensitivity to androgen receptor inhibitors." (PMID 31366128, 2019). "Expression of the androgen receptor splice variant 7 (ARV7) in circulating tumor cells (CTCs) has been associated with resistance towards novel androgen receptor (AR)-targeting therapies." (PMID 31514447, 2019). "Androgen receptor (AR) and ErbB pathways are known to interact, partially overlap and converge on targets downstream of each other’s signaling cascades to promote the survival of androgen-independent cells, leading to androgen-independent PCa tumours." (PMID 30970027, 2019). "The down regulated proteins were associated with genome instability (plasmamix Histon H3 (diMeth K9), Histone H3), the regulation of tumour growth (Androgen receptor, beta-catenin, Bim, Shh), DNA repair (PARP-1) and Notch signaling (Notch 1 intracellular domain (N1ICD), RBPSUH)." (PMID 31758038, 2019). "We combined our genomic findings with AR, FOXA1, and H3K27me ChIP-seq data, and confirmed that important regulators of AR-mediated signaling are located in non-coding regions with open chromatin and highlight the central role of AR signaling in tumor progression." (PMID 31748536, 2019). "In addition, preclinical studies suggest that FOXA1 allows AR to bind to ER DNA binding sites and thereby induce transcription of ER-related genes and thereby stimulate tumor proliferation." (PMID 31888566, 2019). "Blockade of testosterone conversion to estradiol may result in increased AR signaling and subsequently inhibit tumor growth." (PMID 30795773, 2019). "If tumor relapse occurs with a TST level >13 ng/dL, then this tumor may contain more AR-dependent cells, compared to tumors with a relapse occurring with TST < 13 ng/dL." (PMID 30978937, 2019). "Positive staining of the AR protein was found in the nucleus, EphA3 was located in the nucleus and cytoplasm of the PCa tissues, and the adjacent normal prostate tissues all showed faint staining according to the IHC of successive tumor tissue sections." (PMID 30958616, 2019). "Taken together, SW10 cells with activated AR could increase mast cell infiltration into the tumour in vivo and in vitro." (PMID 31852972, 2019). "The current cut-off value of serum TST of 13 ng/dL may represent the remaining AR dependency of the tumor that can only be blocked by treating with novel AR-targeted therapy." (PMID 30978937, 2019). "ARVs may emerge as more common mediators of androgen-independent and AR-dependent tumor progression, although their functions are still unclear." (PMID 31484364, 2019). "In addition, preclinical studies suggest that FOXA1 allows AR to bind to DNA and thereby induce transcription of AR target genes and stimulate tumor proliferation." (PMID 31888566, 2019).
tumor (continued). "Tumour-suppressive, AR-inhibitory miRs such as these could be exploited as therapeutics for PC, alone or in combination with anti-androgens." (PMID 31043708, 2019). "Higher level of androgens in men than in women may be a reason for increased AR protein level and intensification of AR signaling especially at early stages of tumor initiation and progression of BC." (PMID 31119584, 2019). "Therefore, assuming that sPSA reflects the function of AR in the tumor, this result is consistent with our result." (PMID 31664946, 2019). "Blocking these signals could prevent splicing and inclusion of CE3, leading to the expression of a full-length AR mRNA (AR-FL) and this potentially could be used as a mean to re-sensitize tumor cells to current androgen deprivation therapy." (PMID 30664691, 2019). "Thus, in this study, we assessed the correlation between NMIBC recurrence and tumor AR expression in Japanese patients, by quantifying AR mRNA expression with real-time quantitative polymerase chain reaction (RT-qPCR)." (PMID 30961575, 2019). "Interestingly, a small molecule MPC inhibitor, MSDC0160, suitable for clinical studies, induced tumor suppression in models of AR-sensitive and castration-resistant prostate cancer." (PMID 31366128, 2019). "This suggests cells that have passed through a cycle of EMT/MErT may have dysregulation of the AR/androgen-signalling axis and retain biological phenotypes required for sustaining tumour growth and cancer metastasis." (PMID 30194451, 2019). "Finally, we addressed potential contribution of androgen receptor (AR) signaling to the mechanisms favoring STAT5-independent tumor progression in aged mice of the Pb-PRL background." (PMID 31269779, 2019). "Curcumin has been shown to interact with these factors in LNCaP and PC-3 cell lines by inhibiting the expression of the AR, as well as suppressing occupancy at sites of AR function, thus reducing tumour growth and delaying the onset of hormone-resistant disease." (PMID 31540470, 2019). "In addition, we performed IHC staining to analyze AR expression in xenograft tumor tissues from nude mice." (PMID 31761786, 2019). "Moreover, AR amplification has also been detected in circulating tumor cells and cell-free circulating tumor DNA from patients with CRPC." (PMID 31877956, 2019). "Exact molecular mechanisms contributing to androgen independence are unknown, yet recent facts have highlighted the role of tumor microenvironment along with changes in androgen receptor (AR)-related functions." (PMID 29795364, 2018). "In light of the regulatory role of ESR and AR, agents able to modulate these receptors’ gene expression emerges as a fundamental strategy for tumor aggressiveness control, and could potentially be used as new therapies." (PMID 29949923, 2018). "It is now common to observe treatment-resistant tumours with neuroendocrine features upon metastatic biopsy, and the prevailing consensus is that epithelial plasticity enables tumour adaptation in response to AR-targeted therapies." (PMID 29757368, 2018). "The decreased expression levels of stromal AR and PR in high grade PCa could reflect a tumour suppressive role for these SHR." (PMID 30254333, 2018). "Our data indicates that inhibition of USP12 and USP46 activity with galeterone, or other compounds may be a very effective anti-tumour strategy, however galeterone effects in those PC patients expressing AR V may be limited." (PMID 29861848, 2018). "Between marker correlations with likely biological significance were as follows: LN+T-miR-143 was positively correlated with PT stromal AR expression (r = 0.494: p < 0.001), and inversely correlated with PT tumor epithelial PGR expression (−r = 0.453: p < 0.001)." (PMID 29867125, 2018). "In addition, AR knockdown promoted tumor-formation and metastasis capacity, even when cancer cells were xenotransplanted into the mice with a decreased cell density." (PMID 29423076, 2018).
tumor (continued). "Importantly, these tumor experiments provide direct evidence that the AR-KO PCa cells possess intrinsically high tumor-regenerating capabilities in androgen-ablated hosts." (PMID 30190514, 2018). "Moreover, androgen receptor (AR) amplification is concordant between CTCs and tumor tissue biopsies from CRPC patients." (PMID 30034626, 2018). "In androgen-dependent AR signaling, tumor cells can restore the AR signaling pathway by increasing the synthesis of circulating androgens or by acquiring AR gene overexpression, amplification, and mutations that allow AR activation by attenuated levels of androgens following castration or ARPI." (PMID 29666783, 2018). "Thus, AR immunoreactivity in at least 1% of tumor cell nuclei was considered the most appropriate threshold to define AR positivity." (PMID 29883487, 2018). "However, the significance of AR downregulation in androgen insensitivity and de-differentiation of tumor cells in CRPC is poorly understood and much neglected." (PMID 29555975, 2018). "Agonists or inverse agonists for RORα and RORγ might be efficiently inhibiting tumor growth and progression through activation or inactivation so that their ligands or targets, such as vitamin D3 derivatives and AR, become valid or invalid." (PMID 29904382, 2018). "Our data, in particular the aberrant expression of AR in several MEC and oncocytic carcinoma could suggest the potential use of anti-AR drugs also in these tumor types." (PMID 29385707, 2018). "However, AR is an oncogene in triple-negative tumors by “replacing” the estrogen receptor and stimulating tumor growth." (PMID 29949923, 2018). "Overexpression of AR compensates for reduced androgen levels, augmenting continuous tumour growth." (PMID 29682196, 2018). "Compared to the other subgroups, FOXA1-/AR- BC phenotype was more frequently associated with high histological grade, large tumor size, no expression of ER and PgR and high proliferation index (P < 0.001)." (PMID 29970021, 2018). "Finally, it is possible that surgical castration or castration plus ENZ would have had a greater impact on AR signaling and, consequently, PSMA expression, tumor growth, and (AR-mediated) DNA damage repair." (PMID 30374743, 2018). "The lower AR expression in African respect to Caucasian patients might be a consequence of a major tumor aggressiveness (low hormonal receptor expression and highly proliferating tumors) and probably of a different carcinogenesis." (PMID 29651273, 2018). "Patients with AR + /FOXA1 + tumours were significantly older (p = 0.003) than others." (PMID 29880907, 2018). "Indeed, IL-6 has been reported to contribute to the onset of castration-resistant PCa by activating alternative pathways involved in cancer survival and proliferation and by inducing androgen receptor overexpression in tumor cells." (PMID 29896191, 2018). "Therefore, it is pathologically possible that a subset of cancer cells is capable of conditional (hypoxic) androgen/AR-independence, and is selected in the resistant tumor by all types of androgen/AR-blockade strategies." (PMID 30478344, 2018). "In order to elucidate the expression correlation between ERRα and ERG in the progression of castration-resistant prostate cancer (CRPC), we established a CRPC xenograft tumor model VCaP-CRPC based on the castration-relapse growth of AR- and T:E-positive VCaP cells." (PMID 30042415, 2018). "Similarly, positive correlations for tumour/non-tumour LI ratios were found between epithelial AR and stromal ER (r_s = 0.60) and between stromal AR and stromal PR (r_s = 0.57)." (PMID 30254333, 2018). "Patients with AR + /FOXA1 + tumours had a significantly worse OS (p = 0.024)." (PMID 29880907, 2018). "The AR and HSP27 could form a protein complex, which was the main factor in AR regulating the malignancy behavior of tumor cells, and could present a new therapeutic regimen in clinical therapies of MABC." (PMID 29699584, 2018).
tumor (continued). "This is most pertinent when we consider the fact that these compounds are inherently weak androgens with an affinity for the AR which surpasses that of all other steroid receptors that may be present within the tumor." (PMID 30416486, 2018). "The communication between HDAC and Akt therefore seems complex and may depend on the tumor cell line, the androgen receptor status, and the applied HDAC inhibitor." (PMID 30200497, 2018). "In contrast to what could have been expected, bone cell activity was inversely correlated to transcriptional AR activity in tumor cells and to patient serum PSA levels." (PMID 29670000, 2018). "However, a subset of tumor cells will develop mechanisms that help them to bypass their dependency on the AR signaling altogether and progress into AR “indifferent” tumors." (PMID 29666783, 2018). "Consequently, AR and its downstream effectors are attractive therapeutic targets to combat tumor growth in androgen-resistant PCa." (PMID 29967592, 2018). "PDEF+ tumours significantly more often showed AR positivity." (PMID 30217192, 2018). "For AR + /FOXA1 + TNBC with a risk of late relapse, an adjuvant anti-androgen therapy could be considered, like in ER + tumours." (PMID 29880907, 2018). "A subset of the CRCs co-stained for both the AR and p63, which may be indicative of either transient amplifying cells or, in the case of the tumor-derived CRCs, proliferating tumor cells." (PMID 29416764, 2018). "The results showed that HSP27 phosphorylation induced by androgen played a vital role in the process of AR translocation from the cytoplasm to the nucleus, which could affect the proliferation of tumor cells and tumorigenic capacity." (PMID 29699584, 2018). "If tumors with a high ratio of AR:ER expressing circulating tumor cells turn out to be resistant to tamoxifen therapy and this raises the question whether a blockade of AR may be an effective and new target to overcome tamoxifen resistance." (PMID 30547831, 2018). "AR knockdown could promote tumor formation and growth in the mice receiving cancer cells even with a decreased cell number, suggesting an enhanced tumorigenic capability." (PMID 29423076, 2018). "Data regarding clinicopathologic parameters of tumor in relation to AR status are inconsistent." (PMID 30547831, 2018). "AR + /FOXA1 + expression defines a luminal-like TNBC subgroup with a worse outcome compared to other TNBC and a higher risk of late recurrences mimicking luminal tumours behaviour and suggesting a putative role for anti-androgen therapies." (PMID 29880907, 2018). "USP7, besides AR, has different substrates including PTEN and CCDC6, a tumor suppressor protein whose deficiency affects DNA repair mechanism by homologous recombination and sensitizes tumor cells to PARP inhibitors treatment." (PMID 28415632, 2017). "Some studies show AR agonists to actually have anti-tumor effect in the setting of ERα." (PMID 28245550, 2017). "Since AR plays critical role in promoting PCa tumor growth and progression, ENDOD1 is likely to be the mediator of AR signaling in the progression to mCRPC and could possibly be used as markers in predicting the course of disease." (PMID 28532481, 2017). "However, little is known how it suppress the tumor growth and if it can interact with androgen receptor (AR)." (PMID 28287091, 2017). "Indeed, higher levels of AR are thought to sensitize metastatic cells to low intracrine androgen levels expressed by tumor cells." (PMID 28055971, 2017). "In PCa, UPR marker gene activation and tumor progression are linked either by a negative correlation in model systems in vitro, or by a positive association that involves androgens and androgen receptor (AR)." (PMID 28978049, 2017). "Proliferation and AR were increased notably in hyperplasia versus prostate epithelium and tumor." (PMID 28765837, 2017).
tumor (continued). "Continuous IHC nuclear score for BRCA1 correlated positively with CK5/6 (r = 0.24, p<0.0001), basal nature of the tumor (r = 0.52, p<0.0001), bcl2 (r = 0.13, p = 0.04), and AR nuclear (r = 0.33, p<0.0001) scores and negatively with age (r = -0.14, p = 0.048) and tumor grade (r = -0.25, p = 0.01)." (PMID 28863181, 2017). "They found that AR expression was positive in 30% of TNBC, and AR negative is significantly associated with the younger age group, higher grade, and higher tumor stage." (PMID 29069872, 2017). "Finally, a recent study that utilized liquid biopsies and circulating tumor DNA (ctDNA) to probe the AR genomic landscape discovered that patients with AR amplification were less likely to respond to treatment." (PMID 28604629, 2017). "Therefore, we can conclude that the Nintedanib antiangiogenic therapy is a promising strategy for both prevention and intervention of PCa, since it is capable of decreasing neovascularization, AR immunoreactivity and delaying tumor progression." (PMID 28499383, 2017). "Myofibroblasts are the predominant cell type present in the tumour stroma, and although they can be seen to express AR and show physiological and molecular responses to androgens in vivo, primary human fibroblasts shed AR expression within 1–2 passages in culture." (PMID 28117763, 2017). "Finally, our data of AR Pten double knockout in adult basal and luminal cells are consistent with a previous study showing the dispensability of epithelial AR in Pten-null tumour initiation." (PMID 28112153, 2017). "Therefore, we sought to evaluate the AR expression levels in our prostate tissues and to correlate these with tumor grading and NRIP expression." (PMID 28212551, 2017). "YFP+AR− tumour cell clusters were readily detected in the regenerated prostate." (PMID 28112153, 2017). "Two subsequent meta-analyses found that AR expression associated with better outcomes across tumor subtypes, however (i.e., ER positive, ER negative, and TNBC)." (PMID 28085048, 2017). "Some remaining data, however, reveal AR’s tumor-suppressing roles in HCC." (PMID 29312607, 2017). "Studies in cell lines and xenograft models have indicated that ADT can upregulate HER2 and HER3 expression, resulting in the restoration of AR activity and tumor growth in CRPC, while combination with inhibitors against the ErbBs-PI3K-AKT axis can significantly boost the therapeutic effect of ADT." (PMID 29066975, 2017). "Moreover, percentage of papRCCs positive for AR decreased with higher tumor stage and dedifferentiation." (PMID 29108248, 2017). "While AR mutations are relatively rare in untreated hormone-dependent PCa, they are more frequently detected in CRPC, suggesting that ADT may select for tumor cells with alternative activation of AR signaling." (PMID 28036278, 2017). "Of note, there was a great intra- and interpatient heterogeneity of AR expression in normal renal tissue and high AR expression at the site of the tumor was not consistantly associated with high AR expression in the surounding kidney." (PMID 29108248, 2017). "Nineteen patients had AR gene amplification status expressed in CTCs and tumor sample." (PMID 29069718, 2017). "In addition to reciprocally regulating the androgen receptor (AR), PlncRNA-1 knockdown induces tumor cell apoptosis." (PMID 28212533, 2017).